CES1P1 (carboxylesterase 1 pseudogene 1 )
Synonyms: CES1A2; CES1A3; CES4; CESR; PCE-3
Gene: Long non-coding RNA gene on chromosome 16 (55,760,460 to 55,794,158, forward strand). Ensembl gene ENSG00000291109.
Diseases named in the same sentence as CES1P1 in open-access papers:
CES1P1 is named in the same sentence as 4 diseases in open-access papers, as found by Europe PMC text mining. Sharing a sentence is not in itself a finding about the gene and the disease. The quoted sentences say what the papers report.
gastric cancer (1 paper, 2021). A primary or metastatic malignant neoplasm involving the stomach. "CES1P1 are associated with the progression of gastric cancer." (PMID 33765954, 2021).
cancer (1 paper, 2016). A tumor composed of atypical neoplastic, often pleomorphic cells that invade other tissues. "However, a subsequent study of Japanese cancer patients revealed the SNP -816 A>C to reside in CES1P1 and being absent or rare in CES1A2, thus questioning the exact nature of the association with the response to imidapril." (PMID 27662362, 2016).
tumor (1 paper, 2024). "Of note, from RCC42, three deep deletions, UGT2B17, OR4P4 and CES1P1 were consistently observed in both parental tumor and organoid lines." (PMID 38923304, 2024).
CES1P1 also shares sentences with these, for which no sentence is quoted: cervical squamous cell carcinoma (1 paper).